CD4 (CD4 molecule)
Diseases named in the same sentence as CD4 in open-access papers (continued):
Sharing a sentence is not in itself a finding about the gene and the disease.
colorectal cancer (continued). "In addition, we found a significant correlation between CD4+ T cell infiltration density and CD20+ B cell infiltration density in the clinical colorectal cancer cohort." (PMID 35350571, 2022). "In colorectal cancer tissue, CD3+, CD4+, CD8+, and CD45RO+ cells may also be considered to play a critical role in tumor control." (PMID 34572935, 2021). "In colorectal cancer, CXCL16 secreted by cancer cells recruits CD4+ and CD8+ T cells." (PMID 33763372, 2021). "Furthermore, CD4+ T cells that highly expressed the forkhead box P3 (FOXP3) suppressed the anti‐tumor immunity and suggested a poorer prognosis in colorectal cancers." (PMID 34668652, 2021). "Using mass cytometry and single-cell mRNA sequencing, we identify a tumor-infiltrating MAIT cell subset expressing CD4 and Foxp3 and observe high expression of CD39 on MAIT cells from colorectal cancer (CRC) only, which we show in vitro to be expressed specifically after TCR stimulation." (PMID 33205061, 2020). "We found the statistically significant occurrence of fencing clusters formed by a variety of immune cells such as CD4+ /CD8+ T cell subtypes, B cells, NK cells, macrophages, granulocytes, and non-immune cells such as fibroblasts in the TME of lung, HNC, breast, brain, skin, and colorectal cancers." (PMID 41446806, 2025). "Interestingly, a recent preclinical study investigating the efficacy of the DRD2 antagonist Trifluoperazine (TFP) in colorectal cancer reported that tumors from TFP‐treated mice had increased tumor expression of PD‐L1, as well as increased PD‐1 expression on tumor‐infiltrating CD4+ and CD8+ T cells." (PMID 38572507, 2024). "Conversely, the absence of PDL1+ B cells promoted colorectal cancer through CD4+ T cell apoptosis." (PMID 37218867, 2023). "Augmentation of CD4+ T cells, CD8+ T cells and CD49b+ NK cells, as well as increased expressions of IFNg, IL10, CXCR4, and reduced expressions of IL17, STAT3 screened from gene and protein levels, jointly create a microenvironment conducive to inhibit the progress of colorectal cancer." (PMID 37143538, 2023). "Interestingly, the CD4+ T cells in left-sided colorectal tumors had significantly higher levels of oxidative phosphorylation and the TCA cycle than those in right-sided tumors, suggesting a higher T cell function in left-sided colorectal cancers." (PMID 36172359, 2022). "Notably, KRAS wt colorectal cancers exhibited a significantly higher proportion of CD8+ CTLs among T cells but also higher Treg measures (absolute count and the proportion of Tregs among CD4+ cells." (PMID 31307428, 2019). "Similarly, we observed an increased frequency of TIGIT+ cells in both CD4 and CD8 TILs when compared with T cells in peripheral blood from lung, cervical, gastric, and colorectal cancer patients; breast and esophageal cancer patients showed a similar trend, but it was not statistically significant." (PMID 31709176, 2019). "However, RORγt was not expressed within colorectal cancer tissues or by colorectal cancer-infiltrating CD4+ T cells." (PMID 29904382, 2018). "However, the function and phenotype of tumour infiltrating CD4+ T cells in colorectal cancer has not been yet characterized." (PMID 23349906, 2013). "Moreover, SPOCD1 expression was shown to correlate with macrophages and other immune cells (dendritic cells, CD8+ T cells, neutrophils, and CD4+ T cells) by searching the TIMER database, suggesting that these cell types may participate in the immunological immersion process of colorectal cancer." (PMID 36830578, 2023). "Thus, studies here establish not only the safety and efficacy of Ad5-GUCY2C-PADRE in colorectal cancer patients, but also the importance of “split” tolerance (elimination of CD4+ helper, but not CD8+ cytolytic T or B cells) as a mechanism shaping immune responses to self antigens in humans." (PMID 31010434, 2019).
colorectal cancer (continued). "A phase I/II clinical trial in patients with colorectal cancer demonstrated that intramuscular injection of the NCI 4650 vaccine elicited CD8 and CD4 T cell responses to novel antigens, with no significant side effects or tumor recurrence." (PMID 40260289, 2025). "Compared with CEA and CA199, the frequency of CD4+ TSCM in early screening and auxiliary diagnosis of colorectal cancer had no outstanding performance." (PMID 34327142, 2021). "Besides MHC-I, between 20-30% of MMRd colorectal carcinomas show negative or low expression of MHC-II, which is used to present antigens to CD4+ T cells." (PMID 39544936, 2024). "Conversely, no reduction of circulating CD4+/NEO-201+ Tregs was observed at these timepoints in the other 4 patients, all of whom had PD, except for one subject with colorectal cancer that showed a transient reduction of 33.93% at C1D15 vs baseline (2.24% vs 3.39%)." (PMID 36991390, 2023). "However, the effect of light TTM on CD4+ and CD8+ T cells had no change in colorectal cancer patients." (PMID 33808849, 2021).
Allergy (315 papers, 2005 to 2026). An allergy is an immune response or reaction to substances that are usually not harmful. "In summary, severe allergy is associated with reduced intracellular phenylalanine in memory CD4+ Teff cells, most notably in CD161+Th2a enriched cells." (PMID 41308641, 2025). "Patients with severe allergic diseases feature reduced L-phenylalanine transport into CD4+ T cells, leading to expansion of pathogenic Th2 cells." (PMID 41308641, 2025). "In this study, we applied this approach to induce immune tolerance by converting pathogenic CD4+ T cells into Foxp3+ Tregs, thereby extending the therapeutic potential of AP-EVs from cancer to autoimmune and allergic diseases." (PMID 41410284, 2025). "Individuals with DOCK8-deficiency have a high incidence of allergic diseases and eczema, hyper IgE, eosinophilia, and a profound type-2 CD4+ T helper cell (Th2) bias, leading to IL-6 overexpression." (PMID 39044832, 2024). "In this regard, several allergies and autoimmune pathologies are associated with certain alterations to CD4+ tTregs, revealing the true importance of their correct function." (PMID 38203623, 2023). "In summary, hyperleptinemia should negatively impact on the severity of cat allergies by favoring the expansion of pathogenic Fel d1-specific CD4+ T-cell phenotypes and damaging the functional status of regulatory CD4+ T-cell subsets." (PMID 37954580, 2023). "Allergic diseases are immunologic disorders, such as AR disease caused by a decreased CD4/ CD8 ratio and enhanced CD 8+ T cell activation." (PMID 37002325, 2023). "Regarding regulatory CD4+ T cells, the severity of allergic reactions has been associated with functional damage of allergen-specific Treg cells (CXCR5-FoxP3+IL-10+), Tr-1 (CXCR5-FoxP3-IL-10+) and, mainly in IgE-mediated disorders, TFR (CXCR5+FoxP3+IL-10+)." (PMID 37954580, 2023). "Among the subsets of CD4+ T cells, Th2 cells have shown a prominent effect on allergy‐associated inflammatory pathologies, such as AR." (PMID 36149748, 2022). "IL-9-producing CD4 T (Th9) cells have been implicated in allergy and tumor immunity, but how their differentiation is regulated by TGFβ is still unclear." (PMID 36241625, 2022). "Collectively, our results suggested a correlation between intrauterine improper nutrition environment and susceptibility to allergic diseases in offspring later in life via enhanced CD4+ T-cells function." (PMID 35745240, 2022). "Subgroup analyses showed that higher Il-4 and Il-13 transcripts in cord blood CD4+ T-cells were associated with an increased risk of allergic diseases in children of the HC group." (PMID 35745240, 2022). "Increasing efforts to identify homeostatic microenvironments for the formation, survival, and maintenance of allergen-specific memory CD4 T cells have led to a better understanding of the mechanisms underlying allergic disease relapses." (PMID 36591273, 2022). "The underlying cause of allergy is a dysregulation of the fine balance among various branches of the immune system which are orchestrated by specialized subpopulations of CD4+ T cells (e.g., Th1, Th2, Th9, Treg, Th17, Th22)." (PMID 33572097, 2021). "Accumulating data demonstrate that neonatal CD4+ T cells are functionally distinct from that of adults, which directly contributes to the susceptibility to pathogens challenge and allergy development." (PMID 33777965, 2021). "Over the past years, a new subset of CD4 + T named as T helper 9 cells that secrete interleukin-9 (IL-9) as a signature cytokine is associated with tumor immunity and allergy." (PMID 33213045, 2020). "Allergy is characterized by the activation of CD4+ Th2 cells and the production of Th2 associated cytokines, such as IL4, IL5, and IL13, as well as levels of IgE, which activates mast cells." (PMID 33255731, 2020). "Existing therapies for allergic diseases, such as treatment with glucocorticoids and allergen-specific immunotherapy, are associated with the induction of CD4+CD25+ Treg cells." (PMID 29921316, 2018).
Allergy (continued). "Further, CD4 molecules have been reported to participate in allergy associated biological processes." (PMID 28787010, 2017). "We identified that microbiota associated with allergy later in childhood induced increased CD4+ T-cell RORγt expression, and elevated production of IL-17A and IgA, both at local intestinal and systemic sites, indicating expanded Th17 responses." (PMID 29250074, 2017). "Overall, the risk factors for allergies in children of the present cohort included a reduced percentage of CD4+CD25+FOXP3+ T cells, reduced FOXP3 expression, and PPG-stimulated IL-10 secretion." (PMID 27646403, 2016). "We intent to use our eAPC to stimulate primary allergen-specific CD4+ T cells derived from individuals with IgE-associated allergies." (PMID 27539532, 2016). "Since CD4+ T cells producing IL-4 are essential for the class-switch towards IgE and the development of IgE-associated allergy we were interested to investigate the effects of severe CD4+ T cell loss on allergic symptoms and allergen-specific IgE production." (PMID 24896832, 2014). "Although DCs from allergic individuals preferentially induce a Th2-type response, the mechanism underlying by which naïve CD4+ T cells develop to Th2 cells and how this process is out of control is a critical point to elucidate the mechanism of allergy." (PMID 24204099, 2013). "We hypothesized that OIT for cashew allergies would elicit immune tolerance by reducing allergen-specific CD4+ T cells, particularly pathogenic CD4+CRTH2+ Th2A cells." (PMID 41200192, 2025). "Given that Th2 polarization is a hallmark pathological feature of allergic diseases, we investigated whether Kdm4a gene ablation in CD4+ T cells affected allergic responses in the airways." (PMID 41403832, 2025). "While human allergy is typically associated with a Th2 response toward allergens, we and others find the intestinal CD4+ T cell response in the OVA/CT mouse model to be skewed toward proinflammatory Th17, an effect that has been shown to depend on the microbiota." (PMID 37191720, 2023). "Moreover, in human, TH2 cytokines transcripts were enhanced in CD4+ T-cells of the HC group, which was associated with an increased risk of developing allergic diseases at 3 years old." (PMID 35745240, 2022). "In addition, differences in histone 3 and histone 4 acetylation in umbilical cord blood CD4+ T cells have been associated with the development of allergic diseases during childhood." (PMID 35608955, 2022). "ST2 expression on peripheral allergen-specific CD41 T cells is confined to allergy individuals and restricted to Th2A cells and, on circulating CD4+ T cells, represents a transient phenotype associated with Th2A cell activation, allowing these cells to sense locally elicited tissue cytokines." (PMID 36003397, 2022). "A high proportion of CD5+ B cells has previously been shown to be associated with subsequent allergy development, while a high proportion of CD4+ T cells having the FOXP3+CD25high phenotype is associated with a high risk of subsequent sensitization to common environmental allergens." (PMID 33007868, 2020). "Because allergy is definitely associated with MD, it is quite reasonable to conclude that CD4 may be a potential MD-related gene." (PMID 28787010, 2017). "On one hand, PPIA−/− lockout mice developed allergic disease accompanied by elevated IgE and an increased number of mast cells and eosinophils in multiple tissues, which was caused by type 2 cytokines released from CD4+ T cells." (PMID 23110234, 2012). "Additionally, the expression of TRAIL in interferon responsive CD4+ helper (Th) cells and regulatory cells has the potential to impede the activation of Th cells, thereby shedding light on a phenomenon associated with allergic responses." (PMID 40392678, 2025).
Allergy (continued). "T follicular helper cells, a specialized subset of CD4(+) T cells, have been demonstrated to provide help for B cells in the secondary lymphoid organs, which is significantly associated with multiple pathogenesis of diseases, including infectious diseases, allergies, and autoimmune diseases." (PMID 36725968, 2023). "Our previous study indicated that calprotectin may activate DCs and related signal transduction through the action of TLR4 to promote the differentiation of initial CD4 + T cells into Th2-type cells and then cause allergy-related immune responses, leading to the occurrence of allergies." (PMID 34903286, 2021). "After the primary response, circulating memory CD4+T effector and T regulatory (Treg) cells regulate recall responses, typically impaired in allergy." (PMID 41308641, 2025). "(b) Cre recombinase–driven deletion of T cell–specific CFTR in mice provided a powerful approach to assess CD4+ T cell CFTR function in allergy, a method that would be more challenging in larger-animal CF models." (PMID 40131363, 2025). "Collectively, these studies highlight the critical role of stem-like CD4+ T-cell populations in sustaining Th2 responses across allergies, parasite infections, and chronic inflammatory diseases." (PMID 40634636, 2025). "In the context of allergic diseases, the activation of Th2 (T helper 2) cells, along with CD4 + T lymphocytes and B lymphocytes, leads to the manifestation of symptoms such as eczema, allergic inflammation, nasal itching, sneezing, and congestion." (PMID 40371109, 2025). "CD3-positive T lymphocytes are elevated in patients with allergic diseases, and CD4 T cells play critical roles in mediating adaptive immunity-involved AA responses." (PMID 41515303, 2025). "Relevant characteristics of allergen-specific CD4+ T cells related to food-mediated allergic disease present in human PBMCs." (PMID 40574856, 2025). "TSLP has emerged as a crucial trigger in the onset of allergic diseases, owing to its potent capacity to drive naïve CD4+ T cells toward a Th2-dominant phenotype." (PMID 40724851, 2025). "This study highlights the pleiotropic effects of Phe metabolism on proliferation, metabolic reprogramming, and function of human memory CD4+T cell and Th2 cells and provides description of its impairment in severe allergic diseases in humans." (PMID 41308641, 2025). "In situations where homeostasis is disrupted, such as infections, allergies, inflammatory processes, and cancer, local CD4+ T lymphocytes respond to this disruption and, as in the healthy tissue, towards the equilibrium of tissue dynamics." (PMID 38690280, 2024). "It is one of the first and most important modulators that start the Th2 immune response (allergy, parasites) by instigating the cascade of CD4+ T cell, Th2 cell, B cell, and plasma cell differentiation, IgE secretion, and macrophage accumulation." (PMID 39338219, 2024). "Specifically, we demonstrated that Nrf2 activated by tBHQ promotes murine CD4+ T-cell differentiation towards a Th2 lineage in primary mouse CD4+ T cells, a key step in the development of allergy." (PMID 40115160, 2024). "Patients with allergy had higher absolute number (p = 0.027, value w/o IS: p = 0.062) and percentage (p = 0.048, value w/o IS: p = 0.113) of CD4 T cells, and CD4/CD8 ratio (p = 0.006, value w/o IS: p = 0.017)." (PMID 38406025, 2024). "Alterations in DNAm patterns within CD4+ T cells have been observed in allergy patients, correlating with changes in CD4+ T cell counts, particularly in conditions like allergic rhinitis." (PMID 38965641, 2024). "To evaluate the efficacy of P4 therapy in suppressing the Th2 immune response in the airways of mice with OVA-induced allergies, we examined the levels of CD4+ T cells and Tregs in the lungs." (PMID 39060348, 2024). "Other CD4+ T lymphocytes subsets like Follicular T helper (Tfh), Th9, and Th22 cells exhibit distinct functions, contributing to antibody-mediated responses, allergic diseases, and tissue repair." (PMID 38690280, 2024).